DNMT1 (DNA methyltransferase 1)
Diseases named in the same sentence as DNMT1 in open-access papers (continued):
Sharing a sentence is not in itself a finding about the gene and the disease.
cancer (continued). "Moreover, because of the crucial role of PDPK1 downstream PI3‐K/Akt pathway in cancer growth and progression 21, 40 and the reported links of this pathway in the regulation of SP1 and DNMT1 expressions in other studies 33, 38, 41, we also assessed the role of Akt signalling in this study." (PMID 28840963, 2018). "It is able to target E2F Transcription Factor 3 (E2F3), DNA methyltransferase 1 (DNMT1), met proto-oncogene (MET) and Rapamycin-insensitive companion of mTOR (Rictor) and in EC cells it seems to be down-regulated through CpG hypermethylation, promoting cancer development and progression." (PMID 30037059, 2018). "Interestingly, chemokines or chemokine receptors exhibiting consistent hypermethylation and underexpression in cancer, exhibited expression patterns across tumors that were more likely to be consistently negatively correlated with expression of EZH2 or DNMT1 (or both)." (PMID 27899617, 2017). "However, it should be noted that it is DNMT3B, but not DNMT1 or DNMT3A, that has been implicated in aberrant DNA methylation in tumorigenesis for several types of cancer." (PMID 28160561, 2017). "Further reinforcing the importance of recognizing DNMT1-dependent regions for disease, NORED exclusive regions uniquely identified genes that are known to become de novo DNA methylated in cancer and genes that have previously been reported as hypermethylated in cancer." (PMID 29387450, 2017). "Mirza and colleagues reported decreases in the transcript levels of DNMT1, DNMT3A and DNMT3B with the incorporation of WA, and use their findings to suggest that WA may have beneficial therapeutic effects against cancer through its ability to reverse changes in the epigenome." (PMID 28534825, 2017). "It is very likely that these chemokine genes play a tumor suppressor role in cancer, and their consistent negative correlation with expression of epigenetic enzymes such as DNMT1 or EZH2, suggest that their underexpression may be under epigenetic control." (PMID 27899617, 2017). "Given the regulatory role of NFkB in DNMT1 expression, these investigations support the notion that TQ may influence epigenetic events in cancer cells, which has not been studied." (PMID 28415607, 2017). "Moreover, RRx-001 significantly decreased DNMT1 and DNMT3A protein expression in a dose- and time-dependent manner in murine SCC VII cancer cells and induced demethylation of genes important in pathways relevant to cancer." (PMID 28149332, 2017). "MUC1-C induces the expression of DNMT1 and DNMT3b, but not DNMT3a, in carcinoma cells." (PMID 28785086, 2017). "The connection between DNMT1 and KDM1A could be of clinical value, for instance in cancer therapy." (PMID 27449289, 2016). "Finally, we found a correlation between Rb pathway disruption and MEG3 levels in human lung tumors, and taken together, these data suggest that disruption of the pRb-DNMT1 pathway leads to a decrease in MEG3 expression, thereby contributing to the pro-proliferative state of certain cancer cells." (PMID 27832204, 2016). "Interestingly, the findings demonstrate that MUC1-C induces the expression of DNMT1 and DNMT3b, but not DNMT3a, in line with the requirement for both DNMT1 and DNMT3b to silence genes in cancer cells." (PMID 28039441, 2016). "However, results showed that both of DNMT1 and DNMT3a were not significantly changed by TQ treatment in the tested cancer cell lines." (PMID 26023736, 2015). "Furthermore, although the altered methylation pattern observed in HSN1E patients resembles that of tumorigenesis and loss of function of RFTS domain enhances tumorigenicity, none of the DNMT1 mutant patients seem to develop cancer." (PMID 25815005, 2015). "Though DNA methyltransferase-1 (DNMT1) inhibitors, such as 5-azacitidine and its derivatives, are the most well-known demethylating agents, recent studies have also shown that HDACi demethylates regulatory regions of silenced tumor suppressor genes in cancer cells via downregulation of DNMT1." (PMID 24152442, 2013).
cancer (continued). "In addition to specific DNMT1 inhibitors such as AZA and its derivatives, signaling inhibitors could hold promise as future epigenetic therapeutics for cancer." (PMID 24152442, 2013). "However, the precise role of DNMT1 functions in cancer cells is less well understood, since alterations of this gene have not been reported for cancer." (PMID 23638630, 2013). "In addition, over-expression of DNMT3b, but not DNMT1 and DNMT3a, is common in various cancer cells, suggesting that DNMT3b plays an important role in the development of aberrant promoter methylation during oncogenesis." (PMID 17938735, 2007). "Cancer cells may be distinctive in that DNMT1 alone is not responsible for maintaining abnormal gene-specific hypermethylation, and both DNMTs 1 and 3b may cooperate in this action." (PMID 17938735, 2007). "In this study, we found global hypomethylation and increased concentrations of plasma DNA methyltransferases (DNMT1, DNMT3A, and DNMT3B) among cigarette smokers in Saudi compared with non-smokers, which may reflect the molecular mechanisms linking smoking and diseases, such as cancer." (PMID 40003580, 2025). "However, the detailed mechanism of high DNMT1 expression in cancers has not been clear until now." (PMID 36273188, 2022). "Notably for DNMT1, the very small increase in EA intermediates may be due to the cancer types included in the analysis for which DNMT1 is not a driving gene." (PMID 34439147, 2021). "In general, DNMT 3a and 3b are mainly de novo enzymes, while DNMT 1 acts as both maintenance DNMT, which propagates the methylation patterns to the daughter cells (through cell division), and de novo DNMT (non-cell cycle activity) that initiates DNA methylation in cancer cells." (PMID 34203568, 2021). "Most somatic and cancer cells do not express such high levels of the de novo DNA methyltransferases and may not be able to maintain such high levels of DNA methylation in the absence of Dnmt1 activity." (PMID 34906184, 2021). "We discovered that the combination of AH057 and a DNMT1 inhibitor SGI-1027 displayed strong synergistic antitumor effect against CC cells, raising the possibility that synergistically targeting JAK/STAT and DNMT1 might be a promising strategy for effectively treating CC and other human cancers." (PMID 32895373, 2020). "Considering that cancer cells usually divide faster than normal cells and that they have a more stable phenotype throughout successive mitosis, especially under in vitro culture conditions, one might imagine that the DNMT1/UHRF1 tandem is more efficient in cancer cells than non-cancerous cells." (PMID 30669400, 2019). "However, we found the regulation of UHRF1 and DNMT1 in cancer cells by 2i is not universal." (PMID 30696879, 2019). "Since UHRF1 and DNMT1 cooperate to maintain DNA methylation, we reasoned that the anthracycline derivative UHRF1 inhibitors identified here should induce DNA demethylation, and could have synergistic cancer cytotoxic activity with known DNMT inhibitors such as decitabine." (PMID 31105884, 2019). "Indeed, the de novo methylation of genes frequently observed in cancers could be catalyzed by DNMT1, rather than by DNMT3A or DNMT3B." (PMID 30669400, 2019). "Indeed, de novo methylation of genes frequently observed in cancers could be catalyzed by DNMT1 rather than DNMT3A or DNMT3B." (PMID 29449903, 2018). "Pre-existing L1 elements in cultured human cancer cells were stably silenced by dense cytosine methylation, whereas their transcription modestly increased when cytosine methylation was experimentally reduced in cells lacking DNA methyltransferases DNMT1 and DNMT3b." (PMID 28491150, 2017).
cancer (continued). "Furthermore, we have observed no decrease in DNMT1 protein in KDM1A-knockdown cancer cells, suggesting that KDM1A might not affect the stability of the DNMT1 protein in the context of cancer." (PMID 27449289, 2016). "The fact that both DNMT1 and KDM1A have been found, independently, to promote cell cycle progression, including through a replication barrier, suggests that crosstalk between histone demethylation and DNA methylation could be essential in enabling cancer cells to overcome cell cycle checkpoints." (PMID 27449289, 2016). "Thus, our data revealed that the global DNA hypomethylation induced by the DNMT1/PCNA/UHRF1 disruption is an oncogenic event of human tumorigenesis, an inducer of epigenetic and genetic signatures frequently observed in several human cancers, and is an initiator of oncogenic events." (PMID 24637615, 2014). "However, DNMT1 is also required for normal cellular function, e.g. for the inheritance of normal methylation marks during S-phase and therefore unlikely to play a major cancer-specific role." (PMID 22563479, 2012). "In cell-based and in vivo cancer models, only DNMT3B enzymatic activity, and not DNMT1 or DNMT3A, affects Ccnd2 expression." (PMID 36739439, 2023). "RG108 (N-phthalyl-L-tryptophan) is a selective DNMT1 inhibitor and the first small-molecule non-nucleoside DNMT inhibitor to induce demethylation effects in cancer cells." (PMID 37056286, 2023). "In contrast, using qRT-PCR and immunohistochemistry, DNMT1 and DNMT3B expressions were shown to be elevated in carcinomas compared to non-neoplastic tissue and further enhanced in higher-stage carcinomas." (PMID 37894317, 2023). "Unexpectedly, the expression of LEPROT was positively correlated with that of DNMT1 and DNMT3A but not DNMT3B in most cancers and was consistently positive-correlated with DNMT2 in all cancers." (PMID 34804118, 2021). "Therefore, whereas exosomes secreted by normal fibroblasts might impair cancer progression by downregulating DNMT1 and HIF1α in cancer cells through delivering miR-148b and miR-320a, the lack of inhibition by CAFs-derived exosomes could boost the cancer progression." (PMID 34852849, 2021). "We found that 2i broadly down-regulated both UHRF1 and DNMT1, the axis of DNA maintenance methylation, but not de novo enzyme DNMT3A, in various cancer cells." (PMID 30696879, 2019). "Taken together, these data indicated that 2i can broadly but not universally suppress the transcription of DNMT1 and especially UHRF1 in various cancer cell lines." (PMID 30696879, 2019). "Among the nonnucleoside DNMT agents, EGCG stands out as a prominent candidate for cancer therapy due to their ability to bind and block the active site of DNMT1." (PMID 29123614, 2017). "Contrary to published data reported in ES cells, DNMT1 methylation and stability is not influenced by the decreased of KDM1A in cancer cells." (PMID 27449289, 2016). "In contrast, a peptide disrupting the DNMT1/DMAP1 interaction, which per se did not affect tumor growth, sensitized cancer cells to chemotherapy/irradiation-induced cell death." (PMID 23809695, 2013). "Not all of the cancer cell lines expressed the same STAT3 downstream targets but cyclin D1, Bcl-2, survivin, DNMT1 and TWIST1 were among the most common STAT3 downstream targets expressed and were inhibited by the STAT3 inhibitor, FLLL32." (PMID 20712901, 2010). "Although DNMT1 and DMNT3B are also important in cancer development, we did not test the effects of miR-143 on DMNT1 and DMNT3B, because our in silico predictions did not highlight DNMT1 or DMNT3B as the potential binding target of miR-143." (PMID 19638978, 2009).
cancer (continued). "The striking positive correlation between DNMT1 expression and DAC sensitivity across diverse cancer cell lines suggest that the pro-DAC role of DNMT1 is not cell-type specific and underscore the potential of DNMT1 expression as a valuable biomarker to predict patient response to DAC therapy." (PMID 39930152, 2025). "There is some evidence to suggest that decreasing DNMT1 or UHRF1 in non-transformed cells can direct cells towards senescence, but whether this is also true in cancer cells, and the nature of the mechanisms involved, are unclear at present." (PMID 40595593, 2025). "Similarly, the DNMT1, DNMT3A and DNMT3L protein levels were overexpressed and DNMT2 expression was reduced in high-grade carcinomas compared to non-neoplastic tissue and low-grade tumors." (PMID 37894317, 2023). "Interestingly, another study indicates an opposite effect that NF-κB/p65/MUC1-C complex occupy the promoters of DNMT1 and DNMT3B to drive their transcription, but not DNMT3A in carcinoma cells." (PMID 34482802, 2021). "However, despite being functional in the same pathway and frequently overexpressed in cancers, it is not known if the expression of UHRF1 and DNMT1 is coordinately regulated and, if does, by what signaling pathway(s)." (PMID 30696879, 2019). "Thus, the overexpression of DNMT3B, but not DNMT1 or DNMT3A, has been observed in several types of cancers, and suggests an important role for DNMT3B in tumorigenesis." (PMID 28160561, 2017). "Notably, DNMT1, DNMT3A, and DNMT3B are overexpressed in a coordinate manner in most tumor tissues and at a significantly higher level in cancer than in non-tumorous tissues." (PMID 25949795, 2014). "Accordingly, to clarify whether DNMT1 affected miR-497 through methylation regulation, we performed a series of MSP experiments, and observed methylation of CpG island in the miR-497 promoter in cancer tissues, while there was no methylation in normal adjacent tissues." (PMID 35255904, 2022).
tumor (999 papers, 2003 to 2026). "Mechanistically, we found that AMPK regulates DNA methyltransferase 1 to promote transcriptional programs associated with mitochondrial function in the tumor microenvironment." (PMID 40100289, 2025). "Clinical parameters further highlighted the association of DACH1 and DNMT1 expression with tumor differentiation, lymphatic metastasis, and tumor stage." (PMID 40370966, 2025). "Thereby, modulation of miR‐152/DNMT1 through epigenetic mechanisms significantly influences various processes associated with the malignant behaviour of PCa tumours, particularly in AA PCa patients." (PMID 40387409, 2025). "This process triggers the ubiquitination of UHRF1, resulting in the degradation of the DNMT1 protein, which in turn causes abnormal methylation of tumor suppressor gene promoters and promotes cancer development." (PMID 39981244, 2025). "Studies in mouse models have shown that mutations in DNMT1 cause genome-wide DNA hypomethylation, which leads to tumor formation in mice." (PMID 40416611, 2025). "The results revealed a significant association between DNMT1 expression and tumor progression and metastasis in LUSC and LUAD." (PMID 38622665, 2024). "F. nucleatum was confirmed to cause promoter hypermethylation of tumour suppressor genes by increasing the expression of DNMT1 and DNMT3A (DNA methyltransferase) in vitro and in vivo." (PMID 38536233, 2024). "TET2 upregulation and tumor suppressor re-expression were associated with resistance conferred by DNMT1 deletion." (PMID 39057134, 2024). "Upregulation of DNMT1 expression can cause tumor suppressor genes (TSGs) to undergo methylation, thereby inhibiting their expression and promoting tumor development." (PMID 37636435, 2023). "Malignant proliferation of tumor cells induced by gefitinib/osimertinib resistance were due to hypermethylation of the MUC17-specific promoter caused by the UHRF1/DNMT1 complex, which activates the NF-κB signaling pathway." (PMID 36778111, 2023). "Its silencing by the lncRNA H19 is positively correlated with LSCC progression through DNMT1 activation and subsequent hypermethylation of downstream suppressor genes, and significantly associated with tumor grade, differentiation, LNM, and clinical stage." (PMID 35406495, 2022). "We have found significant association between high tumor expression of DNMT1 and shorter OS of LABC patients." (PMID 35719957, 2022). "At low doses, 5-AZA induces DNA hypomethylation via DNMT1 inhibition, causing reactivation of silenced tumor-suppressive genes." (PMID 35327319, 2022). "Our results showed that the D-loop region in bone metastatic tumor cells was markedly hypermethylated than those in primary RCC tumor cells, that is associated with a decreased mtDNA copy number and accumulation of DNMT1 in the mitochondria." (PMID 34976191, 2022). "Many reports in recent years have established the role of miR-148a as a tumor suppressor through its ability to inhibit proliferation by directly suppressing DNMT1 (encoding DNA methyltransferase 1)." (PMID 36010971, 2022). "DNMT1 positively regulates the M1 phenotype and some studies have demonstrated downregulation of M1 markers and increased expression of M2 markers with inhibition of DNMT1; however studies of effects in tumor associated macrophages are lacking." (PMID 33531075, 2021). "The univariable analysis revealed that DNMT1 expression was associated with tumour size and TB, AFP, and PD-L1 levels (P < 0.05)." (PMID 34589490, 2021). "The tumor-associated silencing of HCA2 involves DNA methyltransferase 1 (DNMT1)-mediated DNA methylation." (PMID 33708203, 2021).